ROS1 (ROS proto-oncogene 1, receptor tyrosine kinase)
Diseases named in the same sentence as ROS1 in open-access papers (continued):
Sharing a sentence is not in itself a finding about the gene and the disease.
lung adenocarcinoma (continued). "Exploring the role of rare variants is the next challenge, particularly in ROS1 + NSCLC, in which the access to tumor samples remains difficult due to the low prevalence of ROS1 rearrangements among lung adenocarcinoma patients." (PMID 38433235, 2024). "Although cases of ROS1-rearranged lung adenocarcinomas with pathological psammoma bodies and calcified structures have been reported, there are no documented cases of lung adenocarcinomas with extensive calcification on CT." (PMID 39391406, 2024). "Our findings point towards a relevant contribution of the nucleotide synthesis and cell adhesion pathways to the proliferation of ROS1+ lung adenocarcinomas." (PMID 39737401, 2024). "ROS1 gene rearrangements, resulting in fusion with other partner genes, have been identified in a small proportion of lung adenocarcinomas." (PMID 37627077, 2023). "Here, we report a case of ROS1-rearranged lung adenocarcinoma with concurrent malignant pleural and peritoneal effusion." (PMID 37614510, 2023). "This article presents a case of advanced lung adenocarcinoma with ROS1 rearrangement, characterized by persistent malignant pleural and peritoneal effusion." (PMID 37614510, 2023). "Here, we report acquired MET amplification as a resistance driver in a ROS1-rearranged lung adenocarcinoma after sequential treatment with ROS1 inhibitors." (PMID 37923925, 2023). "ROS1-rearranged lung adenocarcinoma patient had active TME and increased plasma inflammatory factors when the patient received immune therapy and ceritinib chemotherapy." (PMID 36874015, 2023). "The positive ROS1 fusion gene is more common in young, non‐smoking lung adenocarcinoma patients and the analysis of imaging characteristics needs more research data to support." (PMID 37340599, 2023). "Multiple genetic alterations have been identified as therapeutic targets in lung adenocarcinoma, including mutations in EGFR, ERBB2, BRAF, KRAS, and MET and rearrangements of ALK, RET, and ROS1." (PMID 37628603, 2023). "Young (adjusted OR 3.947, 95% CI 1.873–8.314, P < 0.001) and lung adenocarcinoma (adjusted OR 2.950, 95% CI 0.998–8.719, P = 0.050) were associated with ALK/ROS1 fusions." (PMID 35081265, 2022). "Young (adjusted OR 3.947, 95% CI 1.873–8.314, P < 0.001) and lung adenocarcinoma (adjusted OR 2.950, 95% CI 0.998–8.719, P = 0.050) were independent variables associated with ALK/ROS1 gene fusions." (PMID 35081265, 2022). "ROS1 translocation was first identified in lung adenocarcinoma, and later, the consequent ROS1 fusion proteins were found to play significant roles in a variety of cancers, such as FIG-ROS1 in cholangiocarcinoma and inflammatory myofibroblastic tumors." (PMID 35628598, 2022). "Of the 117 patients screened, 49 patients with ROS1-rearranged advanced lung adenocarcinoma were included in our analysis." (PMID 35361870, 2022). "For patients with driver mutations, such as EGFR (10% of NSCLC cases) and BRAF (0.5–4.9% of lung adenocarcinomas), and rearrangements in ROS1 (1–2% of lung adenocarcinomas) and ALK (3–7% of lung adenocarcinomas) gene-targeted therapy can be used." (PMID 35216378, 2022). "The largest case series comprises six cases of lung adenocarcinomas (five with classic EGFR mutations and one with a ROS1 rearrangement) that underwent a sarcomatoid transformation." (PMID 35456982, 2022).
lung adenocarcinoma (continued). "EGFR mutations were more likely to occur in non‐smoking, stage III–IV, and female patients with lung adenocarcinoma, whereas ALK&ROS1 gene fusions were more likely to occur in young patients with lung adenocarcinoma." (PMID 35081265, 2022). "As in lung adenocarcinomas harboring ALK or ROS1 rearrangement, targeted therapy with Crizotinib has been associated with objective responses in IMT." (PMID 33921435, 2021). "Oncogenes were detected in 64% of lung adenocarcinomas, while available information in relation to EGFR, BRAF, KRAS, ALK, ROS1, and MET gene mutations in lung adenocarcinomas are growing steadily." (PMID 34708154, 2021). "And the fusions involving ALK and ROS1 preserved the tyrosine kinase domains of these genes as seen in lung adenocarcinoma." (PMID 33441414, 2021). "The application of tyrosine kinase inhibitors against specific gene targets (EGFR, ALK and ROS1) has revolutionized the treatment for lung adenocarcinoma." (PMID 33738250, 2021). "ROS1 rearrangements are identified in 1–2% of lung adenocarcinoma cases, and reflex testing is guideline-recommended." (PMID 34449580, 2021). "In the same year, an additional novel oncogenic fusion gene, ROS1, was identified, which accounted for 1–2% of all lung adenocarcinoma patients." (PMID 32677962, 2020). "Twenty-three patients who had lung adenocarcinoma with ROS1 rearrangement [5 men and 18 women; mean age of 56 years (range of 31–76 years)] were identified." (PMID 33005033, 2020). "Both KRAS and EGFR mutations are identified almost exclusively in lung adenocarcinomas, similarly to rearrangements involving ALK and ROS1, which were described in 2007." (PMID 32604993, 2020). "Lung adenocarcinomas with ROS1 rearrangement were mainly solid in density (19 of 23, 83%), similar to EGFR-mutant (73%) or ALK-rearranged (88%) tumors, and tended to have a lobulated border (15 of 23, 65%)." (PMID 33005033, 2020). "The fusion gene of EML4-ALK was discovered in lung adenocarcinoma in 2007; since then, fusion alterations of ALK, RET, and ROS1 genes have been found in about 4–7% of patients with lung adenocarcinoma." (PMID 31083279, 2019). "For instance, 50% of Asian patients and 10–15% of Caucasian patients with lung adenocarcinoma are EGFR mutation-positive, with 5% of NSCLC being ALK positive and 1% of NSCLC patients being ROS1 positive." (PMID 31766180, 2019). "For example, crizotinib has been demonstrated to be an effective targeted therapy in patients with lung adenocarcinoma harboring ALK or ROS1 fusions." (PMID 31083279, 2019). "This is the first case report of C-ros oncogene 1 (ROS1)-rearranged putative lung adenocarcinoma presenting as CUP showing a good response to ROS1 inhibitor therapy." (PMID 30443294, 2018). "Here, we report a case of ROS1-rearranged putative lung adenocarcinoma presenting as CUP showing a good response to ROS1 inhibitor therapy." (PMID 30443294, 2018). "Biomarker testing for ROS1 is recommended in all lung adenocarcinoma patients and can be performed using cytogenetic techniques such as FISH using a break apart probe, or molecular techniques including RT-PCR and NGS." (PMID 29914100, 2018). "ROS1 is a receptor tyrosine kinase constitutively activated in about 2% of lung adenocarcinomas as a consequence of fusion gene events." (PMID 30060526, 2018). "In conclusion, we report a case of ROS1-rearranged putative lung adenocarcinoma presenting as CUP showing good response to ROS1 inhibition therapy." (PMID 30443294, 2018). "The frequency of ROS1 rearrangement in putative lung adenocarcinomas is estimated to be low; however, driver oncogenes, including ROS1 rearrangement, should be examined to provide appropriate treatments for patients." (PMID 30443294, 2018). "ROS1-positive lung adenocarcinoma patients have been treated with a combination of crizotinib and lorlatinib, but the data have not yet been published." (PMID 29435193, 2018).
lung adenocarcinoma (continued). "Patients with advanced HER2-mutant lung adenocarcinomas showed an inferior outcome of first line pemetrexed-based chemotherapy compared to those with ALK/ROS1 rearrangements, which strengthen the need for effective HER2-targeted drugs in clinical practice." (PMID 29587667, 2018). "We first identified and reported interstitial lung disease induced de novo by crizotinib in a 47-year-old female patient who was diagnosed with advanced lung adenocarcinoma with a ROS1 rearrangement in a malignant pleural effusion." (PMID 30029601, 2018). "Driver oncogenes, such as ROS1 rearrangement, EGFR mutation, and ALK rearrangement, should be examined in putative lung adenocarcinoma similar to that in primary lung adenocarcinoma." (PMID 30443294, 2018). "Some specific histological features have been reported in lung adenocarcinomas with ALK or ROS1 fusions, such as a mucinous cribriform pattern or solid growth pattern with signet ring cells." (PMID 29163763, 2017). "For example, KRAS mutations are frequently detected in lung adenocarcinomas in smokers, whereas genetic alterations in EGFR, ALK, ROS1, and RET are frequently detected in lung adenocarcinomas in non-smokers." (PMID 28894699, 2017). "Data describing the morphologic features of ROS1-rearranged lung adenocarcinomas are primarily based on analysis of resected primary lung tumors." (PMID 27708233, 2016). "A correlation between histomorphology and ROS1-rearranged lung adenocarcinomas has been demonstrated in prior reports." (PMID 27708233, 2016). "The majority of ROS1-rearranged advanced lung adenocarcinomas in our series showed a solid growth pattern (75%, 12/16)." (PMID 27708233, 2016). "We found that ROS1-rearranged advanced lung adenocarcinomas were characterized by two growth patterns: solid growth (12/16) and acinar (4/16) growth." (PMID 27708233, 2016). "Thirty‐four patients including 16 males and 18 females with lung adenocarcinoma were identified as ROS1 translocation with a frequency of 1.9% (34/1750)." (PMID 27544536, 2016). "Our study revealed that 3.7% (19 out of 516) of advanced lung adenocarcinomas harbored ROS1 rearrangement." (PMID 27708233, 2016). "Most literature reported ROS1 rearrangement in 1-2% adenocarcinoma lung, but more than 3% in IV-stage lung adenocarcinoma." (PMID 27708233, 2016). "Lung adenocarcinomas have shown more driver mutations that can be successfully targeted such as EGFR, ALK, ROS1." (PMID 26371045, 2015). "Recent genomic studies in lung adenocarcinoma have identified other potential therapeutic targets, such as mutations in KRAS, HER2 and BRAF, ROS1 rearrangements, RET fusions and MET amplification." (PMID 25789627, 2015). "Rearrangements to the c-ros oncogene 1, receptor tyrosine kinase (ROS1) gene are reported in 1–2% of lung adenocarcinomas." (PMID 25364439, 2014). "C-ros oncogene 1, receptor tyrosine kinase (ROS1) gene rearrangements are reported in 1–2% of lung adenocarcinomas and are sensitive to the small-molecule tyrosine kinase inhibitor crizotinib." (PMID 25364439, 2014). "In the present study, we demonstrated that IHC is an effective screening tool for the detection of ROS1 rearrangements in lung adenocarcinomas." (PMID 25058391, 2014). "Major recurrent mutations in lung adenocarcinoma have been found to occur in EGFR, KRAS, HER2, BRAF, ALK and ROS1." (PMID 22140546, 2011). "Entrectinib is an example of an ROS1 inhibitor that can be used for lung adenocarcinoma." (PMID 39802058, 2025). "In this report, we present a rare case of lung adenocarcinoma with the coexistence of short and long variants of the MYH9–ROS1 fusions, which may affect the efficacy of ROS1-TKI targeted therapy." (PMID 39854762, 2025). "In contrast, the lung adenocarcinoma showed neoplastic cells with abundant vacuolated/eosinophilic cytoplasm, prominent nucleoli, and TTF‐1 immunoreactivity, findings that could be seen in ROS‐1 rearranged lung adenocarcinoma." (PMID 40028792, 2025).
lung adenocarcinoma (continued). "The major clinical implications that can be retrieved from our study are mainly directed towards SLC34A2-ROS1 rearranged lung adenocarcinomas and, according to our spheroid drug assay, all the 5 TKIs evaluated effectively targeted ROS1 wild type and S1986Y mutant cells." (PMID 38433235, 2024). "Here, we present a case of extensively calcified lung adenocarcinoma with ROS1 fusion." (PMID 39391406, 2024). "We report a case of extensively calcified lung adenocarcinoma with ROS1 fusions." (PMID 39391406, 2024). "ROS1 rearrangements typically occur in lung adenocarcinomas, rarely in adenosquamous carcinoma." (PMID 38953007, 2024). "Here, we present a case of extensively calcified lung adenocarcinoma with ROS1 fusions." (PMID 39391406, 2024). "Previous study suggested that females and never smokers with lung adenocarcinoma are more likely to harbor EGFR/ALK/ROS1 mutation." (PMID 39000058, 2024). "However, cytopathological and mutational analyses of the pericardial fluid confirmed the diagnosis of ROS1-rearranged lung adenocarcinoma, and an adequate therapeutic effect was obtained by oral administration of entrectinib." (PMID 39559635, 2024). "Therefore, directly comparing ROS1+ lung adenocarcinomas with ALK+ or RET+ tumors, while excluding cell lines, provides further insights into the tumor microenvironment." (PMID 39737401, 2024). "However, given the single case report nature, the efficacy of this regimen in treating advanced ROS1-rearranged lung adenocarcinoma should be considered as a supplementary strategy, warranting further validation through multicenter clinical data." (PMID 37614510, 2023). "Similarly, the correlation among oncogenic mutations in ROS1, ALK, EGFR and PD-L1 had been reported in lung adenocarcinoma." (PMID 36874015, 2023). "ROS1 fusion genes have been detected in other cancer types, such as glioma and lung adenocarcinoma." (PMID 37537783, 2023). "However, a switch in SCLC also occurs in lung adenocarcinoma with other driver mutations such as ALK and ROS1 foreshadowing possible more complex mechanisms." (PMID 35456982, 2022). "For instance, several tyrosine kinase inhibitors, targeting EGFR, ALK, RET receptor tyrosine kinase (RET), and proto-oncogene tyrosine-protein kinase ROS (ROS1), are the standard of care for lung adenocarcinoma (LUAD) patients carrying corresponding molecular mutations." (PMID 35740511, 2022). "At our institution, somatic mutation detection using immunochemistry and NGS Panel CLv3 and single tests for ROS1 and ALK mutations was performed for nearly all lung adenocarcinoma patients at the time of diagnosis, and finally, almost half of them had negative findings (42%)." (PMID 36292136, 2022). "However, this non-reciprocal/reciprocal ROS1 translocation, containing a novel ROS1-FBXL17 fusion co-existing with the CD74-ROS1 fusion, was found in a Chinese patient suffering from lung adenocarcinoma, who responded well to treatment with crizotinib." (PMID 33572278, 2021). "Several oncogenic drivers have been identified in lung adenocarcinoma, including mutations in the epidermal growth factor receptor (EGFR), fusions of anaplastic lymphoma kinase (ALK), and rearrangements of ROS proto-oncogene 1 receptor tyrosine kinase (ROS1)." (PMID 32677962, 2020). "In this case, we identified a novel ROS1 fusion gene in a lung adenocarcinoma patient." (PMID 31382924, 2019). "Moreover, mutation of ROS1, BRAF, RET, NTRK1, PIK3CA, and MEK1 occur in only 1% of lung adenocarcinoma." (PMID 31766180, 2019). "The ROS1 IHC has shown good sensitivity and specificity as a surrogate marker for ROS1 rearrangement in lung adenocarcinomas, but recent studies showed much lower specificity in gastric adenocarcinomas (3/23) and cholangiocarcinomas (0/72) when compared to NGS assays." (PMID 31221175, 2019).
lung adenocarcinoma (continued). "The tumor specimen was also examined as an advanced primary lung adenocarcinoma and assessed for the following tumor markers: epidermal growth factor receptor (EGFR) mutation, anaplastic lymphoma kinase (ALK) rearrangement, ROS1 rearrangement, and programmed death-ligand 1 (PD-L1) expression." (PMID 30443294, 2018). "Lung adenocarcinomas harboring oncogenic driver mutations at the level of EGFR and ROS1 and ALK rearrangements have a lower mutational load, often occur in never smokers and are sensitive to targeting with specific inhibitors and this offered new therapeutic perspectives for these patients." (PMID 30060526, 2018). "ROS1 fusion genes were found in 1–2% of lung adenocarcinoma patients." (PMID 29435193, 2018). "Interestingly, lung adenocarcinomas associated with specific driver mutations, such as EGFR, ALK or ROS1 display a specific pattern of CpGs methylation." (PMID 30060526, 2018). "We determined the ROS1 status of 1750 patients with lung adenocarcinoma." (PMID 27544536, 2016). "In IV-stage lung adenocarcinoma, 3.4% (11/327) were ROS1-rearranged." (PMID 27708233, 2016). "Crizotinib combined with palliative operation and radiation therapy (WBRT plus boost to residual brain metastasis) in the treatment of ROS1 fusion gene positive lung adenocarcinoma with symptomatic brain metastases, can effectively control intracranial lesions with good tolerance." (PMID 27561802, 2016). "Thus, it is essential to find out the features of advanced lung adenocarcinoma with ROS1 rearrangement." (PMID 27708233, 2016). "Patients diagnosed with ROS1 translocation lung adenocarcinoma may benefit from pemetrexed‐based chemotherapy." (PMID 27544536, 2016). "Aberrant fusions involving the ROS1 gene occur in about 1.5% of lung adenocarcinomas." (PMID 26371045, 2015). "ROS1 fusion has been shown to contribute to the formation of lung adenocarcinoma." (PMID 22140546, 2011). "Besides contrasting these findings using publicly available data, in this study we hypothesized that ROS1+ NSCLC is defined by specific transcriptomic signatures compared to other oncogene-driven tumors like ALK+ or RET+ lung adenocarcinomas." (PMID 39737401, 2024). "Thus, this case was identified as ROS1- rearranged putative lung adenocarcinoma presenting as CUP." (PMID 30443294, 2018). "Second, ROS1 inhibitor therapy may be effective for ROS1-rearranged putative lung adenocarcinoma." (PMID 30443294, 2018). "However, a case series study reported prolonged PFS with pemetrexed as first-line and maintenance therapy in patients with ROS1-driven lung adenocarcinoma, indicating that patients in this subgroup may be optimal candidates for pemetrexed chemotherapy." (PMID 29361925, 2018). "First, putative lung adenocarcinoma presenting as CUP may have ROS1 rearrangement." (PMID 30443294, 2018). "Furthermore, we identified independent predictors for ROS1 rearrangement, built prediction model for ROS1-rearranged NSCLCs by multiple logistic regression analysis, and tested the performance of prediction model on a new cohort of 57 lung adenocarcinomas (53 ROS1- and 4 ROS1+)." (PMID 27648828, 2016). "We identified 27 cases of ROS1-rearranged lung adenocarcinomas in 1165 patients with NSCLCs confirmed by real-time PCR and FISH and performed univariate and multivariate analyses to identify predictive factors associated with ROS1 rearrangement and finally developed prediction model." (PMID 27648828, 2016). "A total of 1356 lung adenocarcinoma cases from April 2007 to May 2013 were sequenced for EGFR kinase domain mutations, KRAS mutations, HER2 kinase domain mutations, BRAF mutations, ALK fusions, ROS1 fusions, RET fusions and AKT1 mutations." (PMID 26486077, 2015). "In this study, we applied IHC, FISH, and qRT-PCR analysis in a large collection of ROS1-positive cases, and compared the specificity and sensitivity of IHC assay with other methods for the detection of ROS1 fusion in patients with primary lung adenocarcinoma (ADC)." (PMID 25742289, 2015).